SARM1 (sterile alpha and TIR motif containing 1)
Diseases named in the same sentence as SARM1 in open-access papers (continued):
Sharing a sentence is not in itself a finding about the gene and the disease.
cervical cancer (3 papers, 2018 to 2025). A primary or metastatic malignant neoplasm involving the cervix. "We have previously reported that cervical cancer cell lines expressing E6 and E7 from high-risk HPV types have several alterations on the TLR pathway, such as increased expression of HMGB1, SARM1 and TLR415." (PMID 35468924, 2022). "Here we show that the expression of IL6 and IL18 is modulated by TLR4 and SARM1 in cervical cancer cells." (PMID 35468924, 2022). "To determine if TLR4 and SARM1 impact the response of cervical cancer cells to chemotherapy, we treated parental, TLR4KO and SARM1KO cells with different concentrations of cisplatin." (PMID 35468924, 2022). "To study the role of TLR4 and SARM1 in the malignant phenotype of cervical cancer cells, we knocked out these genes individually in HeLa cells using CRISPR/Cas9 and isolated individual clones of the edited cells." (PMID 35468924, 2022). "In conclusion, TLR4 and SARM1 are important for therapy resistance and cervical cancer cell viability and may be relevant clinical targets." (PMID 35468924, 2022). "Interestingly, while MyD88 was downregulated in cervical cancer cell lines, SARM1 expression levels were upregulated." (PMID 29472602, 2018). "Here, we sought to further dissect the function of the TLR pathway in a cervical cancer cell line focusing on the roles of TLR4 and SARM1 on cell survival and cisplatin resistance." (PMID 35468924, 2022). "Here, we studied the receptor TLR4 and the adaptor molecule SARM1 in HeLa cells, an HPV-positive cervical cancer cell line." (PMID 35468924, 2022). "First, we observed that the adaptor molecule MyD88 was downregulated whereas SARM1 and TLR4 were upregulated in all three cervical cancer cell lines relative to normal keratinocytes." (PMID 29472602, 2018).
experimental autoimmune encephalomyelitis (3 papers, 2022 to 2024). An autoimmune demyelinating disease of the central nervous system that is produced experimentally in animals by the injection of homogenized brain or spinal cord in Freund's adjuvant. "Interestingly, astrocytes do appear to upregulate expression of SARM1 in response to spinal cord injury and also to modulate neuroinflammation in experimental autoimmune encephalomyelitis." (PMID 37091921, 2023). "Here, we established the MS model of mice - experimental autoimmune encephalomyelitis (EAE) and found that SARM1 was upregulated in astrocytes of the spinal cords of EAE mice." (PMID 36055989, 2022). "However, in an experimental autoimmune encephalomyelitis/optic neuritis model, neither SARM1 inhibition strategy improved retinal ganglion cell survival." (PMID 39076204, 2024).
glioblastoma (3 papers, 2022 to 2025). The most malignant astrocytic tumor (WHO grade IV). "This correlation also occurred for SARM1 protein levels, with the exception of the glioblastoma cells U87MG and U251." (PMID 40955574, 2025). "Collectively, these data indicate a correlation between SARM1 levels and Vacor sensitivity, except in glioblastoma cell lines." (PMID 40955574, 2025). "Resistance to the chemical might be ascribed to the ability of glioblastoma cells to undergo only partial (50%) NAD depletion after prolonged Vacor exposure, suggesting sub‐lethal SARM1 activation levels in glioblastoma." (PMID 40955574, 2025). "SARM1 activation further depleted the residual NAD in FK866-treated cells, again suggesting that reversible activation of SARM1 might be a viable strategy for enhancing the efficacy of FK866 in glioblastoma therapy." (PMID 39336077, 2024). "In summary, our results demonstrate that SARM1 could be a viable drug target for NAD-depletion strategies in glioblastoma therapy." (PMID 39336077, 2024). "Specifically, while MEFV and STAT3 expression was detected in both glioblastoma cells and immune cells, SARM1 expression level was higher in NPC-like and OPC-like glioblastoma cells than in MES-like, AC-like glioblastoma cells, and other tumor cells." (PMID 35990696, 2022). "We found, indeed, that two glioblastoma cell lines express relatively high levels of SARM1 but do not display Vacor sensitivity." (PMID 40955574, 2025).
injury (3 papers, 2018 to 2022). Damage inflicted on the body as the direct or indirect result of an external force, with or without disruption of structural continuity. "Sarm1 knockout mice showed reduced clinical severity and reduced axonal loss in animal models of traumatic brain injury." (PMID 32584865, 2020). "While we cannot discount possible indirect effects of 129/Ola derived genes, our data are nonetheless consistent with the known role of SARM1 in response to brain injury and its activity as an NADase, as well as its ability to regulate mitochondrial biogenesis." (PMID 35507602, 2022). "Notably, Sarm1 was found to improve acute responses in a mouse model of traumatic brain injury, where crush and shear injuries to axons are more typical." (PMID 30010873, 2018).
Leber congenital amaurosis (3 papers, 2021 to 2022). Leber congenital amaurosis (LCA) is a retinal dystrophy defined by blindness and responses to electrophysiological stimulation (Ganzfeld electroretinogram (ERG)) below threshold, associated with severe visual impairment within the first year of life. "However, recent studies do suggest direct involvement of SARM1 in neuronal cell death in some situations, including photoreceptor loss in models of retinal degeneration and Leber congenital amaurosis (LCA) and as a result of Vacor neurotoxicity when specifically applied to cell bodies." (PMID 34796871, 2021). "Previous studies from our lab and others have shown that SARM1 has a pro-degenerative role in inherited retinopathies, using models of retinitis pigmentosa and Leber Congenital Amaurosis (LCA)." (PMID 35431772, 2022).
multiple sclerosis (3 papers, 2020 to 2025). A progressive autoimmune disorder affecting the central nervous system resulting in demyelination. "SARM1 may be involved in neuronal axonal damage and demyelination in MS (multiple sclerosis)." (PMID 41018229, 2025). "EAE alone may not adequately capture the impact of targeting SARM1 on neurodegeneration in multiple sclerosis." (PMID 32584865, 2020). "One possible explanation for the finding that Sarm1 deletion results in early but not late axonal protection is that the primary mechanistic drivers of axonal degeneration may differ between early and late axonal degeneration in EAE and multiple sclerosis." (PMID 32584865, 2020).
ZIKV infection (3 papers, 2022 to 2025). "To identify which NADases contribute to the loss of NAD+ homeostasis during ZIKV infection, we analyzed the mRNA expression of Sarm1, Cd38, and Cd157 in the brains of ZIKV-infected neonate mice over the course of infection." (PMID 41362627, 2025). "The initial trigger for SARM1-dependent degeneration of neuronal processes following ZIKV infection could act through gain or loss of function, for example, through cytotoxicity, failure of trophic support from neighboring glia, or a combination of both." (PMID 35493328, 2022). "Our data provide novel evidence of a SARM1-dependent mechanism of degeneration of neuronal processes following ZIKV infection." (PMID 35493328, 2022). "Unexpectedly, ZIKV infection led to a rapid SARM1-independent reduction in NAD+." (PMID 35493328, 2022). "Surprisingly, this pro-degenerative role of SARM1 appeared to be independent of its NADase activity, although ZIKV infection itself caused NAD+ depletion in all three Sarm1 genotypes." (PMID 35493328, 2022). "Consistent with this notion, SARM1 has been shown to regulate axon degeneration during lyssavirus (Sundaramoorthy and others 2020) and Zika virus infections (Crawford and others 2022), although the downstream pathways may differ from injury-induced degeneration." (PMID 37002660, 2024). "Axon degeneration induced by lyssavirus is regulated by NAD+ loss and calpain activation (Sundaramoorthy and others 2020), while Crawford and others (2022) showed that NAD+ loss observed following Zika virus infection is independent of SARM1 NADase activity at 24 h postinfection." (PMID 37002660, 2024). "Irrespective of the cellular localization of NAD+ depletion, it appears that the mechanism by which SARM1 contributes to degeneration of neuronal processes following ZIKV infection is independent of its NADase activity." (PMID 35493328, 2022). "At 24 hpi, staining of DAPI +ve cell nuclei revealed little difference between infected cultures of either of the three Sarm1 genotypes and their mock-infected controls, suggesting the absence of overt ZIKV infection-related cell death at this time point, as quantified previously." (PMID 35493328, 2022). "Together, these data identify a role for SARM1 in the pathogenesis of ZIKV infection, which may reflect SARM1's conserved prodegenerative function, independent of its NADase activity." (PMID 35493328, 2022).
autism (2 papers, 2022 to 2024). Persistent deficits in social interaction and communication and interaction as well as a markedly restricted repertoire of activity and interest as well as repetitive patterns of behavior. "We next explored the cellular mechanisms by which the loss of the Sarm1 gene in PVIs caused autism-like behavior features." (PMID 35869039, 2022). "Our study revealed that knocking out SARM1 in PVI caused an autism-like behavioral phenotype and resulted in increased PVI apoptosis in mice." (PMID 35869039, 2022). "Sterile alpha and TIR motif-containing 1 protein (SARM1) is known as an autism-associated protein and is enriched in brain tissue." (PMID 35869039, 2022). "In this study, we showed that selectively knocking out SARM1 in PVIs causes autism-like behavior, including social deficits, repetitive grooming, and comorbidity with anxiety disorder in mice." (PMID 35869039, 2022). "To further evaluate the association between SARM1 and autism, we checked the expression level of SARM1 protein in two autism mouse models (Fmr1-/y, LPS-induced autistic mice)." (PMID 35869039, 2022). "Based on the expression pattern of SARM1 and the pivotal role of PVIs in autism pathogenesis, we speculate that loss of SARM1 in PVIs may have an effect on social interaction." (PMID 35869039, 2022). "Taken together, our results implied the association of SARM1 with autism pathogenesis." (PMID 35869039, 2022). "In conclusion, conditional knockout of SARM1 in PVIs resulted in the autism-like phenotype of SARM1PV-CKO mice by affecting the number or functions of PVIs." (PMID 35869039, 2022). "For LPS-induced autism mice, it has been reported that the expression level of SARM1 is upregulated in cultured neuronal cells treated with LPS." (PMID 35869039, 2022). "The relative SARM1 protein levels in these two autism model mice were upregulated in the cerebral cortex and hippocampal regions." (PMID 35869039, 2022). "Many ASD-risk genes are involved in synaptic connections by regulating pre- or postsynaptic structures during development, encouraging the possibility that neuronal-specific conditional SARM1 knockout may show autism-like phenotypes." (PMID 35869039, 2022). "In our study, upregulation of SARM1 protein was found in the brain tissue of two autism mouse models, Fmr1 KO mice and an LPS-induced MIA mouse model, which could represent a genetic model and an environmental model of ASD." (PMID 35869039, 2022). "Moreover, SARM1 knockdown mice exhibit autism-like behaviors." (PMID 35869039, 2022).
autism spectrum disorder (2 papers, 2022 to 2024). A spectrum of developmental disorders that includes autism, and Asperger syndrome. "Taken together, our results indicate that the expression of SARM1 in PVIs plays a vital role in the pathogenesis of autism spectrum disorder." (PMID 35869039, 2022).
Charcot-Marie-Tooth disease type 2 A (2 papers, 2025). "Of particular interest is the role of SARM1 in degeneration induced by mitochondrial dysfunction, such as in Charcot-Marie-Tooth disease type 2A (CMT2A), which is caused by mitofusin mutations that disrupt mitochondrial outer membrane fusion." (PMID 40344041, 2025).
Charcot-Marie-Tooth neuropathy (2 papers, 2023 to 2024). "In the Charcot-Marie-Tooth neuropathy model with mitochondrial abnormality, SARM1 deletion preserved mitochondrial morphology and motility, and protected axons and synapses from degeneration." (PMID 37292715, 2023).
colitis (2 papers, 2021). Inflammation of the colon. "Given the clinical interest in modulating Sarm1 activity, a critical question is raised by this study: what causes Sarm1 activation and eventual axon degeneration in colitis?" (PMID 33900577, 2021). "Despite its positive effect of blocking the pathological degeneration of catecholaminergic axons, we were surprised to observe that the Sarm1 deletion significantly exacerbated the colitis condition, as evidenced by the worsened body-weight loss and disease activity index." (PMID 33871822, 2021). "Unexpectedly, the blockage of such axonal degeneration by the Sarm1 deletion in mice exacerbated the colitis condition." (PMID 33871822, 2021). "However, we unexpectedly revealed that blockage of such axonal degeneration by the Sarm1 deletion in mice exacerbated the colitis condition." (PMID 33871822, 2021). "In addition, Sarm1+/+-BMCMs and Sarm1−/−-BMCMs underwent a similar course of colitis, as monitored by the daily change of body weight, suggesting that Sarm1 expressed in immune cells would likely not be involved." (PMID 33871822, 2021).
glioma (2 papers, 2022 to 2024). A benign or malignant brain and spinal cord tumor that arises from glial cells (astrocytes, oligodendrocytes, ependymal cells). "SARM1 also suppresses glioma progression by inhibiting the proliferation of glioma cells and regulating microglial polarization." (PMID 39336077, 2024). "Meanwhile, SARM1, a regulatable NAD-consuming enzyme, has exhibited significant implications in glioma progression and cellular death regulation." (PMID 39336077, 2024).
hepatocellular carcinoma (2 papers, 2015 to 2018). A malignant tumor that arises from hepatocytes. "At the same time, the GPC3 gene inhibits hepatocellular carcinoma cells, and plays an important role in immunity, while sterile α and TIR motif containing one (SARM1) genes are also related to immunity, and are responsible for regulating neuronal inflammation." (PMID 29187421, 2018).
Insulin resistance (2 papers, 2024 to 2026). Increased resistance towards insulin, that is, diminished effectiveness of insulin in reducing blood glucose levels. "Knockout of SARM1 in mice leads to a significant activation of insulin resistance-related pathways including AKT, GSK3β, IRS1, and FOXO1, thereby alleviating insulin resistance in mice fed a high-fat diet." (PMID 39021599, 2024). "Beyond neuroscience, emerging studies reveal that SARM1 may also drive aspects of bone fragility, liver pathology, adipose expansion, and insulin resistance in metabolic disease." (PMID 42068248, 2026).
ischemia (2 papers, 2024 to 2025). A hypoperfusion of the BLOOD through an organ or tissue caused by a PATHOLOGIC CONSTRICTION or obstruction of its BLOOD VESSELS, or an absence of BLOOD CIRCULATION. "Our first aim was to evaluate whether eliminating SARM1 activity can enhance long-term RGC survival in focal axonal ischemia, using the rat rNAION model in a recently developed rat SARM1(−) knockout line generated in an SD rat strain using Crispr-Cas9 technology." (PMID 38334594, 2024). "Thus, eliminating SARM1 activity improves both RGC survival and the quality of the surviving axons after axonal ischemia." (PMID 38334594, 2024). "This suggests that inhibiting or eliminating SARM1 activity is likely to be neuroprotective in conditions involving non-absolute stressors such as partial axonal ischemia." (PMID 38334594, 2024).
metabolic syndrome (2 papers, 2023 to 2024). A cluster of metabolic risk factors for CARDIOVASCULAR DISEASES and TYPE 2 DIABETES MELLITUS. "Furthermore, SARM1 genetic deletion prevents the development of distal sensory axonal degeneration in metabolic syndrome." (PMID 38400192, 2024).
neuroblastoma (2 papers, 2025 to 2026). Neuroblastoma (NB) is the most common solid, extracranial childhood tumor. "Here, we show a tight link between apoptotic and SARM1-dependent degeneration by demonstrating that SARM1 is activated during and contributes to apoptosis in neuroblastoma cells, macrophages, and T cells." (PMID 41576094, 2026). "However, when we silenced SARM1 in the Neuro2a neuroblastoma cell line, which undergoes lower NAD depletion kinetics compared to SH‐SY5Y cells after Vacor exposure, we found that silencing completely prevented Vacor‐dependent NAD depletion." (PMID 40955574, 2025).
ocular hypertension (2 papers, 2024). Abnormally high intraocular pressure. "Conversely, in a silicone oil-induced ocular hypertension model, SARM1−/− mice or SARM1-targeting antisense oligonucleotide injections demonstrated neuroprotection for both retinal ganglion cell somas and axons." (PMID 39076204, 2024). "Animals that received adenoviral injection and developed ocular hypertension will be referred to as B6 OHT or Sarm1 KO OHT for the remainder of the manuscript." (PMID 38331947, 2024).
prion disease (2 papers, 2022 to 2024). A transmissible disease that is caused by a protein that is able to induce abnormal folding of normal cellular proteins, leading to characteristic spongiform brain changes, which are associated with neuronal loss without an inflammatory response. "SARM1 has been proposed to have a protective effect in prion disease, and we hypothesized that it its role in regulating mitochondrial energetics may be involved." (PMID 35507602, 2022). "Rather, they simply suggest another mechanism whereby the NADase function of SARM1 and its role in regulating mitochondrial respiration could also contribute to slowing prion disease progression." (PMID 35507602, 2022). "Our data suggest that SARM1 slows prion disease progression, likely by regulating mitochondrial respiration, which may help to mitigate oxidative stress via NRF2." (PMID 35507602, 2022). "We have shown that prion disease is accelerated in mice in which SARM1 has been ablated." (PMID 35507602, 2022). "Pathologically, disease was similar in both strains of mice, suggesting that SARM1 mediated axonal degradation is not the sole mechanism of axonal loss during prion disease." (PMID 35507602, 2022). "Thus, SARM1-mediated regulation of mitochondrial respiration via its NADase activity may help to determine the tempo of prion disease progression." (PMID 35507602, 2022). "That study concluded lack of SARM1 led to an upregulation of the pro-apoptotic gene Xaf1, leading to an increase in neuronal apoptosis and shorter prion disease incubation times." (PMID 35507602, 2022). "We have also found that faster prion disease incubation times correlated with increased mitochondrial respiration in prion infected mice lacking the molecule SARM1, a protein that may also be involved in the PINK1/Parkin pathway of mitophagy." (PMID 38394123, 2024). "Our data suggest that SARM1 is important in regulating mitochondrial respiration and may influence expression of NRF2 in the brain, functions which could help to mitigate the progression of prion disease and possibly other neurodegenerative protein misfolding diseases." (PMID 35507602, 2022).
retinal diseases (2 papers, 2020). "As NAD+ loss is a common pathology of many retinal diseases, this raises the possibility that SARM1 activation may contribute to a wide range of retinal disorders." (PMID 33107823, 2020).